ATP1B1 (ATPase Na+/K+ transporting subunit beta 1)
Diseases named in the same sentence as ATP1B1 in open-access papers (continued):
Sharing a sentence is not in itself a finding about the gene and the disease.
glioblastoma (1 paper, 2020). The most malignant astrocytic tumor (WHO grade IV). "We analyzed the FAIM2, DLGAP2, ATP1B1 and RALYL alterations using the cBioPortal online tool for Glioblastoma Multiforme (TCGA, Firehose Legacy)." (PMID 33323543, 2020).
heart failure (1 paper, 2025). Inability of the heart to pump blood at an adequate rate to meet tissue metabolic requirements. "AC6 proximal protein prostacyclin synthase is also upregulated upon hypertrophy and heart failure, while ATP1B1 encodes the beta subunit of the sodium potassium ATPase which is essential for the myocardial resting membrane potential and is often associated with cardiovascular disease." (PMID 40749829, 2025).
Huntington disease (1 paper, 2025). Huntington disease (HD) is a rare neurodegenerative disorder of the central nervous system characterized by unwanted choreatic movements, behavioral and psychiatric disturbances and dementia. "We selected HIP1R, ATP1B1, and WDR4 to validate the proteomic results, as they are associated with Huntington’s disease, neuronal axon regeneration, and neurological disorders, respectively." (PMID 40001624, 2025).
kidney damage (1 paper, 2023). "In addition, these 106 potential classifiers/biomarkers between TCMR vs. STA are associated with kidney damage (e.g., ATP1B1, CST3, FAH, GSS, HPX and LYZ), tubule injury (e.g., CRYM, GSS, HAGH, HPX and LYZ) and kidney inflammation (e.g., DCN)." (PMID 36814924, 2023).
Listeria infection (1 paper, 2025). "Listeria infection further led to the loss of Na+/K+-ATPase subunits ATP1A1 and ATP1B1, and loss of Afadin and Nectin-3, suggesting a disruption of junctional integrity and polarity upon cell invasion." (PMID 41510227, 2025).
medulloblastoma (1 paper, 2015). A malignant, invasive embryonal neoplasm arising from the cerebellum. "Analysis of two publicly available datasets, GSE3526 and GSE37418, revealed that compared to normal cerebellum, human medulloblastoma tumors showed decreased ATP1B1 and increased Bmi1 levels across all subgroups with a p-value of 4.1e-07 (ATP1B1) and 9.2e-28 (Bmi1)." (PMID 26286140, 2015).
melanoma (1 paper, 2020). A malignant, usually aggressive tumor composed of atypical, neoplastic melanocytes. "Finally, eight genes (GPR87, KIT, SH3GL3, PVRL1, ATP1B1, CDAN1, FAU, and TNFSF14) were identified to be closely associated with the OS in melanoma." (PMID 32411243, 2020). "In our study, we identified two gene expression patterns and generated an 8-gene-based (GPR87, KIT, SH3GL3, PVRL1, ATP1B1, CDAN1, FAU, and TNFSF14) gene signature that could recognize melanoma patients with a high risk of unfavorable clinical outcomes." (PMID 32411243, 2020). "Our signature consists of diverse genes comprising protective (ATP1B1, CDAN1, FAU, and TNFSF14)) and risky (GPR87, KIT, SH3GL3, and PVRL1), which could be considered gene-related protective and risk patterns in melanoma." (PMID 32411243, 2020). "We identified an 8-gene signature (i.e., GPR87, KIT, SH3GL3, PVRL1, ATP1B1, CDAN1, FAU, and TNFSF14) with independent prognostic value on melanoma." (PMID 32411243, 2020). "All eligible gene sets were analyzed, and the 8 genes (GPR87, KIT, SH3GL3, PVRL1, ATP1B1, CDAN1, FAU, and TNFSF14) with the greatest prognostic impact on melanoma." (PMID 32411243, 2020).
neuritis (1 paper, 2012). A neuropathy arising from inflammation of one or more nerves. "Also, genes involved in nervous system development were found, for example ATP1B1 (involved in aggregation of neurons), TRIM2 (neuroprotection of cortical neurons) and VAPA, SGK1 and ZFYVE27 (involved in morphogenesis of neuritis)." (PMID 23028713, 2012).
nonalcoholic steatohepatitis (1 paper, 2022). "We provide evidence that inhibiting ATP1B1 might be effective for treating nonalcoholic steatohepatitis." (PMID 36072588, 2022).
Obesity (1 paper, 2025). Accumulation of substantial excess body fat. "Furthermore, obesity led to the up-regulation of sodium transporters (Slc13a1, Slc22a8, Slc17a1, Slc17a3) and the down-regulation of structural proteins (Col4a3, Col4a4) as well as Na/K-ATPase subunits encoded by Atp1a1, Atp1b1, suggesting impaired sodium metabolism and underlying renal injury." (PMID 41133844, 2025).
pancreatic cancer (1 paper, 2025). "Finally, NRG1 fusion partners were most commonly ATP1B1 (pancreatic cancer) or CD74 (NSCLC) in FDA-approved indications, with a mix of these as well as SLC3A2 and RBPMS being commonly observed partner genes in nonapproved indications." (PMID 41091579, 2025).
retinal disease (1 paper, 2018). "In conclusion, the TEP across the RPE depends on the expression of ATP1B1 and this regulates the secretion of PEDF by RPE cells and so may regulate the onset of retinal disease." (PMID 30160348, 2018).
schizophrenia (1 paper, 2022). A major psychotic disorder characterized by abnormalities in the perception or expression of reality.
venous thromboembolic disease (1 paper, 2022). "Also, inhibition of ATP1B1, a gene positively associated with the CAD-risk in MR, is predicted to increase the risk of venous thromboembolic disease." (PMID 35246263, 2022).
cancer (15 papers, 2007 to 2025). A tumor composed of atypical neoplastic, often pleomorphic cells that invade other tissues. "The data show that the mRNA transcript encoding Na K-ATPase (Atp1b1) was elevated in the cancer cell lines compared to the normal cell lines and exhibited altered expression profiles between AA and CAU cell lines." (PMID 17472751, 2007). "For instance, genes like SLC24A3, GALM, MPO, and ATP1B1 appear to be commonly down-regulated across various solid cancers, while other MRGs are frequently up-regulated in many cancer types." (PMID 38995414, 2024). "ATP1B1 is the key subunit of Na+/K+ ATPase, playing an important role in the maintenance of adhesion among cancer cells via modulation of tight junctions." (PMID 38003694, 2023). "Next, we inoculated immunodeficient mice with ATP1B1-knockdown cancer cells and treated them with paclitaxel." (PMID 37966117, 2023). "Our findings align with those of previous studies suggesting that ATP1B1 may function as a potential suppressor of cancer progression, as evidenced by its upregulation in treatment-responsive patients without metastasis." (PMID 40834150, 2025). "We then performed shRNA-mediated knockdown of ATP1B1 in patient-derived cancer cells." (PMID 37966117, 2023). "ATP1B1 has been identified as a biomarker of prognosis and treatment response in different cancer settings, which suggests that it may be a globally important predictive biomarker." (PMID 35820911, 2022). "NKA β1 subunit (ATP1B1) is downregulated in human epithelial cancer cells." (PMID 33868261, 2021). "We hypothesized that the level of ATP1A1 expressed in this cancer cell line exceeds that of its obligate partner ATP1B1, and thus ATP1A1 is recognized by HSP70/HSC70 constitutively in these cells." (PMID 32687490, 2020). "Interestingly, yarrow-Sep inhibited key lipid metabolic targets in CRC cells extensively shown to be implicated in cancer dissemination and prognosis —SREBF1, FASN, ABCA1 and HMGCR— and epithelial to mesenchymal targets—CDH1, ATP1B1, CDH2 and Vimentin—augmenting cell adhesion." (PMID 38576446, 2024). "Thus, FXYD3 and ATP1B1 may cooperatively maintain the activity of the Na+/K+ pump and, consequently, support drug resistance in ancestor-like CSCs while working independently in other cancer cells for other functions." (PMID 37966117, 2023). "As ccRCC progresses, increased methylation of the promoter of ATPase Na/K transporting subunit beta 1 (ATP1B1) decreases its expression in cancer, thereby inhibiting tumor progression and acting as a cancer suppressor." (PMID 37035172, 2023). "The comparison of the individual relative densities of cancer cells in both cell line models between AA and CAU women revealed altered expression in 5 of the 14 potential biomarkers (Atp1b1, CARD 10, KLF4, Spint2, and Acly)." (PMID 17472751, 2007).
tumor (13 papers, 2015 to 2025). "For the spatial visualization of RNA and gene expression, we found that the prognostic genes from XGBoost model, especially GNAS, ATP1A1, ATP1B1, colocalized with the densest regions of tumor." (PMID 39678375, 2024). "The combined treatment with paclitaxel and ATP1B1 knockdown markedly inhibited tumorigenesis and led to tumor regression." (PMID 37966117, 2023). "Some genes, such as MT2A, NEAT1, ATP1B1, and C11orf96, were highly expressed in tumour cells from ccRCC1." (PMID 34168986, 2021). "Among these genes, we identified several factors that were related to tumor progression and were found to be consistent with previously reported, for example, CAT, ATP1B1, CCND1, and CXCL12." (PMID 38020927, 2023). "The main functions of the top genes in OSPC2 network were associated to sensitization to chemotherapy (CXCR4, ANKRD1, CYR61, EDN1, ATP1B1, ARHGEF1, RTF1), and tumor suppression (FGFR3, BCL11B)." (PMID 28482906, 2017). "ATP1B1, GPC3, KCNIP3, and PRLR transcript levels in tumor tissues were significantly lower in PTCs than in NT, whereas LCN2, LGALS1 and SCD1 expression was upregulated in PTC compared with NT." (PMID 27249794, 2016). "On the contrary, women with ERα-positive BC have a significantly higher survival probability when the tumor expresses high levels of ATP1A1 or ATP1B1 while no significant changes in RFS of women with ERα-positive BC have been evidenced considering the ATP1A2 mRNA expression." (PMID 36232400, 2022).
neurological disease (2 papers, 2018 to 2025). "There were three proteins associated with neurological disease as well as tissue development, including ADP/ATP translocase 2 (Slc25a5), 2′,3′-cyclic-nucleotide 3′-phosphodiesterase (Cnp), and sodium/potassium-transporting ATPase subunit beta-1 (Atp1b1)." (PMID 30127667, 2018).
neurodevelopmental disorder (1 paper, 2015). A behavioral and cognitive disorder with onset during the developmental period that involves impaired or aberrant development of intellectual, motor, or social functions. "Summary of CNVs involving KIRREL3 interacting proteins MYO16, MAP1B, and ATP1B1 in patients with neurodevelopmental disorders." (PMID 25902260, 2015).
renal disease (1 paper, 2023). "Among these genes, Adora2b, Trpc5, Ar, Xrcc2, and Atp1b1 are involved in renal disease and blood pressure regulation." (PMID 37125041, 2023).
ATP1B1 also shares sentences with these, for which no sentence is quoted: keratoconus (2 papers); adenocarcinoma (1); ampullary carcinomas (1); autosomal dominant polycystic kidney disease (1); cardiovascular disease (1); Cirrhosis (1); clear cell renal cell carcinoma (1); colon tumor (1); depression (1); diabetic kidney disease (1); diabetic retinopathy (1); Dupuytren’s Disease (1); eosinophilia (1); Fuchs endothelial corneal dystrophy (1); gastric cancer (1); geographic atrophy (1); glomerulonephritis (1); head and neck cancer (1); kidney inflammation (1); lung carcinoma (1); lymphoma (1); osteoporosis (1); polycystic kidney disease (1); psoriasis (1); serous ovarian tumors (1); squamous cell carcinoma (1); type 2 diabetes mellitus (1).